PRAMEF8 (PRAME family member 8)
Synonyms: PRAMEF24
Tractability: No criterion of Open Targets' tractability assessment is met for any kind of drug.
Gene: Protein-coding gene on chromosome 1 (13,281,304 to 13,285,137, reverse strand). Ensembl gene ENSG00000182330.
Gene Ontology:
Molecular function: ubiquitin-like ligase-substrate adaptor activity
Biological process: proteasome-mediated ubiquitin-dependent protein catabolic process; negative regulation of apoptotic process; negative regulation of cell differentiation; negative regulation of DNA-templated transcription; positive regulation of cell population proliferation
Cellular component: Cul2-RING ubiquitin ligase complex; cytoplasm
Genetic constraint (gnomAD): Loss-of-function variants: 1 observed, 5.07 expected, observed/expected ratio (o/e) 0.2, 90% interval 0.069 to 0.93. That is too few expected variants to judge how well the gene tolerates losing a copy. Missense variants: 12 observed, 128.56 expected, observed/expected ratio (o/e) 0.0933, 90% interval 0.059 to 0.15. Synonymous variants: 4 observed, 44.74 expected, observed/expected ratio (o/e) 0.0894, 90% interval 0.043 to 0.2.
Homologues: Orthologues: mouse Pramel12 (48% identical), rat Pramef8 (48% identical), mouse Pramel13 (47% identical), rat Pramef12 (46% identical), mouse Gm13040 (45% identical), mouse Gm13043 (45% identical), mouse Gm13057 (45% identical), mouse Pramel31 (44% identical), mouse Pramel20 (44% identical), mouse Pramel16 (44% identical), mouse Pramel43 (44% identical), mouse Pramel46 (44% identical), and 78 more. Paralogues in human: PRAMEF7 (99% identical), PRAMEF12 (84% identical), PRAMEF6 (63% identical), PRAMEF5 (63% identical), PRAMEF15 (62% identical), PRAMEF20 (62% identical), PRAMEF9 (62% identical), PRAMEF25 (62% identical), PRAMEF26 (62% identical), PRAMEF27 (62% identical), PRAMEF11 (62% identical), PRAMEF4 (61% identical), and 12 more.